TNF (tumor necrosis factor)
Diseases named in the same sentence as TNF in open-access papers (continued):
Sharing a sentence is not in itself a finding about the gene and the disease.
ischemia (continued). "The present study showed that the effect of use of MK-886 (6 mg/kg) before induction of ischemia and at the onset of reperfusion caused significant lowering (P < 0.05) in serum levels of the IL-6 and TNF-α." (PMID 22196041, 2011). "TNF-α is associated with the propagation of heart failures such as myocardial hypertrophy and ischemia and has a critical role in intermediary metabolism; therefore, its deregulation could contribute to the development of cardiovascular diseases." (PMID 40243563, 2025). "One study suggested that TNF-α-308G/A polymorphism is associated with ST-elevation myocardial infarction and high plasma levels of biochemical ischemia markers, and a meta-analysis demonstrated a significant association between TNF-α-308G/A and the risk of acute myocardial infarction." (PMID 37629366, 2023). "IR may increase the release of inflammatory factors such as C-reactive protein and tumor necrosis factor, leading to the adhesion and aggregation of leukocytes, which can cause retinal capillary obstruction and finally local ischemia." (PMID 38130393, 2023). "In addition, plasma sST2 correlated with plasma TNF-α, which can cause direct and indirect neuronal injury through ischemia, spontaneous demyelination, and induction of the deaths of neurons and oligodendrocytes." (PMID 35800259, 2022). "In our animal study, the mRNA level of IL-6, TNFα, and IL-1β was increased 24 h after ischemia induction; this was associated with the presence of M1-like macrophages and the expansion of cerebral infarction although the mRNA level of IL-6 was low during the first 3 h." (PMID 29110250, 2018). "However, retinal ganglion cell loss after ischemia has been described in many previous studies, and the TNF-α–lowering effect of etanercept is also apparent." (PMID 27259948, 2016). "Moreover, Ginkgo biloba treated I/R group showed significantly decreased plasma levels of IL1-β and TNF-α compared to I/R group and caused improved histological disruption of spermatogenesis observed in ischemia only and I/R groups." (PMID 28101298, 2016). "This probably results from the fact that TNF-α is involved in the production of nitric oxide and induction of vasodilation and hypotension, which may cause renal ischaemia and hypoxia, and finally acute tubular necrosis and renal failure." (PMID 24553975, 2014). "Thus, we speculated that loss of TNF-α under steady state probably make neurons susceptible to ischemia, while acute blocking increased soluble TNF-α in the injured brain could be neuroprotective." (PMID 37486903, 2023). "The overall goal of the current study was to determine if increased levels of TNFα protein in cerebral tissue, as may be found in human brain after ischemic stroke, will exacerbate memory impairment after ischemia and contribute to the risk of vascular cognitive impairment (VCI)." (PMID 27144978, 2016). "During the acute phase of ischemia, a rapid increase in TNF-α levels, primarily originating from activated microglia, leads to the predominant activation of the TNFR1 receptor." (PMID 41683844, 2026). "Typical inflammatory pathways such as cytokine-cytokine receptor interaction, TNF signaling pathway, and NF-κB signaling pathway further indicated an activated inflammatory cascade in the ischemia brain." (PMID 41328343, 2026). "Exosomes derived from MSCs can ameliorate inflammation after acute ischemia or ischemia–reperfusion injury by modulating anti-inflammatory molecules (IL-4 and IL-10) and pro-inflammatory cytokines (IL-6, TNF-α, and IL-1β), and inhibiting microglia activation." (PMID 40771978, 2025). "Cardiac ischemia–reperfusion results in a marked decline in cardiac function, a decrease in left ventricular pressure, and a decrease in cardiac TNF-α levels during ischemia but an increase after perfusion." (PMID 40284832, 2025).
ischemia (continued). "Carthamus tinctorius L. [Asteraceae; Carthami flos] reduces cerebral infarction and neurological deficits in ischemia-reperfusion injury and cerebral infarction models by mitigating free radicals and pro-inflammatory cytokines, including TNF-α and IL-1β." (PMID 41438511, 2025). "TNF-α plays a critical role in the progression of ischemia by promoting the release of endothelial adhesion molecules, activating leukocytes, and inducing the secretion of thrombocyte-activating factors." (PMID 41511355, 2025). "During the acute phase of ischemia, microglia are activated to secrete cytokines such as TNF-α, IL-1β, and IL-6, which further exacerbate the destruction of BBB." (PMID 40260076, 2025). "Macrophages play a central role by forming foam cells and secreting pro-atherogenic cytokines, such as TNF-α, IFN-γ, and IL-1β, which destabilize atherosclerotic plaques, expanding the lipid core and increasing the risk of thrombosis and ischemia." (PMID 40243563, 2025). "HSPA1A was shown to inhibit the production of proinflammatory factors (TNF-α and IL-6) and inhibit the activity of matrix metalloprotein kinases (MMPs) and iNOS in both in vitro and in vivo models of ischemia." (PMID 39924492, 2025). "In line with our previous study, we observed that renal epithelial cells expressed low levels of NF-Kβ, TNF-α, and IL-6 when cyclic hind limb ischemia was performed during bilateral ischemia (BIR + RIPerC group)." (PMID 41239227, 2025). "Especially, the pro-inflammatory phenotype of microglia induced by ischemia and LPS is characterized by increasing productions of iNOS, IL-1β, IL-6, TNF-α, reactive oxygen species (ROS) and NO resulted in the dysfunction of the CNS." (PMID 40289983, 2025). "Cardiac myocytes produce TNF-α during ischemia that has direct deleterious effects on heart muscle cells, including apoptosis and depressing contractile function." (PMID 41511355, 2025). "When brain cells are damaged by ischemia, neurons, microglia, and vascular endothelial cells produce TNF-α." (PMID 41471340, 2025). "Proinflammatory cytokines, such as TNF-alpha, IL-1, and IL-6, are increased and further exacerbate the inflammatory response following ischemia." (PMID 40949500, 2025). "In the hyperacute phase, astrocytes are activated in response to TNF, microglia engage in phagocytosis, and there is an increase in Stat3‐induced ischemia‐responsible OPCs and senescent LECs." (PMID 40799188, 2025). "TNF-α acts through the typical proinflammatory NF-κB signaling cascade to exert its harmful effects in ischemia." (PMID 40949500, 2025). "Microglia, the primary mediators of neuroinflammatory processes in the CNS, respond to various pathological changes, including injury, ischemia, and infection, by expressing a range of cytokines like IL-1β, IL-6 and TNFα." (PMID 38600587, 2024). "Nesfatin-1 reduced microglia proinflammatory activation by decreasing IL-1β, IL-6, and TNFα expression in a rat ischemia model." (PMID 39295865, 2024). "Low doses of TNF can rapidly activate the transcription factor NF-kB, which in turn mediates the cardioprotective effects of various forms of ischemia and drug preconditioning." (PMID 39024234, 2024). "They demonstrated curcumin’s protective role in intestinal ischemia-reperfusion injury through modulation of zonula occludens-1 (ZO-1) protein expression and downregulation of the TNF-α pathway." (PMID 39765622, 2024). "In isolated rat hearts, ischemia alone was sufficient in increasing the TNFα levels in a time-dependent manner." (PMID 38256155, 2024). "IL-1β, TNF-α, and NFκB-p65 mRNA expression levels were significantly increased in the ischemia and I/R groups in comparison to the healthy group (P<0.05)." (PMID 37886007, 2023). "Inflammatory signaling is activated and completed by blood-derived leukocytes, which penetrate the brain during ischemia and produce inflammatory cytokines and proinflammatory mediators, including TNF-α, IL-6, and ICAM-1." (PMID 37361203, 2023).
ischemia (continued). "According to various inducing factors, necroptosis is divided into tumor necrosis factor-α(TNF-α)-induced external necroptosis, intrinsic necroptosis induced by reactive oxygen species (ROS), and endogenous necroptosis induced by ischemia." (PMID 36834481, 2023). "Another study in a rat model showed that the TNF-α gene level was highly elevated in injured kidney tissues in rats that underwent a right kidney nephrectomy and ischemia in the left kidney for 45 minutes, followed by reperfusion." (PMID 37305825, 2023). "MiR-181c was found to directly target tumor necrosis factor-alpha (TNF-α) after ischemia, thereby regulating microglia activation and microglia-mediated neuronal injury in vitro." (PMID 35524670, 2023). "Administration of Captopril, Losartan, or their combination resulted in a significant (p < 0.01) decrease in TNF-α, IL-1β, and IL-6 levels which was increased at the beginning by ischemia compared to untreated controls." (PMID 37259385, 2023). "As the iris is a metabolically active tissue, pro-inflammatory cytokines (interleukin-6, prostaglandin E2, and tumor necrosis factor-alpha) are released following surgical injury, trauma, or ischemia." (PMID 38983009, 2023). "And inflammatory factors, such as TNF-α, produced by activated M1 type microglia can form a vicious cycle of neuroinflammation and exacerbate ischemia-induced inflammatory injury." (PMID 37519758, 2023). "Activated microglia serve a dual role during ischemia, releasing pro-inflammatory cytokines (such as TNF-α and IL-1β) that can aggravate ischemic injury, whilst promoting the release of anti-inflammatory cytokines (such as IL-10) to reduce ischemic injury." (PMID 36725745, 2023). "The anti-inflammatory effects of Tat-CHIP were assessed in the hippocampus 6 h after ischemia induction by measuring pro-inflammatory cytokine levels, such as IL-1β, IL-6, and TNF-α." (PMID 36450819, 2022). "In primary rat cerebellar neuronal-glial cell cultures affected by ischemia, propolis significantly protected the cultures from hypoxia-induced elevation of TNF-α, IL-1β and IL-6." (PMID 36500579, 2022). "Another study demonstrated that cross-linking TIM-1 and TIM-4 in macrophages results in TNF-α/IL-6 secretion and contributes to ischemia reperfusion-induced liver damage." (PMID 35990621, 2022). "The neuroprotective mechanisms of 6 mg/kg purpurin were evaluated in terms of anti-inflammatory responses in the hippocampus using an ELISA assay for IL-1β, IL-6, and TNF-α 6 h after ischemia." (PMID 35094304, 2022). "Kefir fed to rats for 30 days via oral gavage decreased serum urea, creatinine, and tumor necrosis factor-alpha (TNF-α) concentrations after aortic ischemia and reperfusion." (PMID 36106262, 2022). "High expression of SNHG14 increases the expression of lipoprotein-related phospholipase by inhibiting miR-145-5p, which promotes the release of a large number of inflammatory cytokines (TNF-α, NO) after ischemia and aggravates neuronal damage." (PMID 36275741, 2022). "and ischemia induced TNF-α, IL-8, and monocyte chemoattractant peptide and triggered inflammatory response during wound repair." (PMID 35359679, 2022). "In fact, miR-329 has been implicated in the modulation of inflammatory responses during ischemia, since knockdown of its expression inhibits the release of TNF-α and nitric oxide in the supernatant of OGD-stimulated microglial cells." (PMID 35359933, 2022). "In the current study, AKI did result in significant increase in levels of TNF-α and IL-6 in the blood, kidney and hypothalamus at 24 h after ischemia." (PMID 35530034, 2022). "The release of inflammatory factors, such as TNF-α has been found to have a crucial role in mediating and exacerbating ischemia/reperfusion injury." (PMID 35812319, 2022). "IL-1β, IL-6, and TNF-α levels were significantly decreased 4 days in the hippocampus after ischemia compared to 6 h post-ischemic group, respectively." (PMID 35094304, 2022).
ischemia (continued). "Using a coculture system, Tezel and Wax showed that glia cells secreted TNF-α when exposed to simulated ischemia, which promoted the direct death of RGCs." (PMID 35637215, 2022). "The release of inflammatory factors (e.g., TNF-α, IL-6, and IL-1β) after ischemia-induced macrophage activation is responsible for IR damage and for exacerbating liver microcirculation disorders." (PMID 35966821, 2022). "Astrocytes have been found to produce inflammatory cytokines, including IL-6 and TNFα, following traumatic injury and ischemia." (PMID 34071762, 2021). "mRNA levels of proinflammatory cytokines, IL-1α, IL-6, and TNF-α, were significantly higher in the I/R group 2 h after the reperfusion period following ischemia compared with the control group (IL-1α, p < 0.05; IL-6, p < 0.0001; TNF-α, p < 0.01)." (PMID 33843175, 2021). "We observed the levels of IL-6, IL-1β, and TNF-α in the hippocampus 6 h after ischemia because these pro-inflammatory cytokines are increased biphasically, with a prominent increase at this early period after ischemia." (PMID 33435613, 2021). "Differently from models of permanent ischemia, results from transient MCAO are instead pointing more clearly toward a protective role of anti-TNF-α treatments in ischemia/reperfusion brain injury." (PMID 33770265, 2021). "Similar to what observed in the heart, TNF-α plays pivotal roles in the pathophysiology of ischemia and ischemia/reperfusion injuries in the brain during ischemic stroke." (PMID 33770265, 2021). "Several stimuli including glutamate, IL-1α, hypoxia, TNFα, and reactive oxygen species seen in ischemia can activate NF-κB." (PMID 33953854, 2021). "AP39 also exerted prominent anti-inflammatory activity in reducing the release of Il-1β, Il-6 and TNFα in brain areas particularly affected by ischemia." (PMID 34360581, 2021). "In the present study, transient ischemia significantly increased lipid peroxidation and pro-inflammatory cytokines IL-1β, IL-6, and TNF-α in the hippocampus 6 h after ischemia." (PMID 34203930, 2021). "During ischemia, cytokines, such as IL-1β, IL-6 and TNF-α are produced by a variety of activated cell types, including microglia and neurons (Huang, Upadhyay & Tamargo, 2006)." (PMID 34123580, 2021). "In the Tat peptide- and Control-SH3GL2-treated groups, TNF-α, IL-1β, and IL-6 levels were significantly increased in the hippocampus 6 h after ischemia compared to those in the control group." (PMID 33572372, 2021). "Meanwhile, low doses of TNF-α has also been shown to prevent hepatocellular apoptosis and liver damage in inflammatory as well as in ischemia/reperfusion-induced liver injury." (PMID 33746949, 2021). "TNF-α, IL-1β, and IL-6 are the major pro-inflammatory cytokines that aggravate the inflammatory response after ischemia injury." (PMID 34238326, 2021). "The expression of serum IL-6 and TNF-α in the mild hypothermia therapy group was significantly lower than that in the ischemia reperfusion group." (PMID 34422094, 2021). "Hydrogen gas inhalation has been proven to decrease the levels of inflammatory cytokines, including TNF-α, IL-1β, and IL-6, in ischemia/reperfusion injury or the retina, liver, and brain." (PMID 34769482, 2021). "In ischemia and obstructive-induced nephropathy, TNFα is identified as an important mediator of tubular cell apoptosis." (PMID 33934104, 2021). "In summary, the pretreatment with GPE-R significantly promotes the survival of neurons in the hippocampal CA1 region after ischemia/reperfusion by reducing reactive microglia and pro-inflammatory cytokines such as IL-6, IL-1β, and TNF-α." (PMID 33435613, 2021). "In another intestine-ischemia model, EA lowered TNF-α, IL-8, intestinal permeability to fluorescein isothiocyanate (FITC) dextran in plasma and increased intestinal ZO-1 protein expression." (PMID 35095910, 2021).
ischemia (continued). "We found that CSO treatment significantly inhibited the hyperactivation of microglia and astrocytes and significantly decreased the expression levels of proinflammatory cytokines (IL-1β, IL-6, and TNF-α) in the ischemia penumbra after MCAO-R injury." (PMID 32917229, 2020). "Neutrophils, natural killer cells, and natural killer T cells are recruited to the kidney within hours of ischemia; these immune cells release proinflammatory molecules, such as interleukin-1, interleukin-6, and tumor necrosis factor (TNF)-α." (PMID 33150250, 2020). "Enhanced levels of TNF-α expression have been observed following ischemia in both the brain and cardiac tissue." (PMID 31923917, 2020). "Our previous report demonstrated that TNF-α pretreatment at a concentration of 20 ng/mL showed the highest survival rate of hNPCs in ischemia-related in vitro conditions, and we therefore mainly used this concentration in this study." (PMID 32403417, 2020). "LAM treatment significantly decreased TNF-α and iNOS expression in the ischemia group compared with that of the ischemia and ischemia + saline groups (n = 3/group; P < 0.05)." (PMID 31926564, 2020). "Microglia respond rapidly to brain injury including ischemia to produce excessive pro-inflammatory and neuro-modulatory cytokines such as tumor necrosis factor (TNF) and interleukin family members." (PMID 32117296, 2020). "Both inflammatory factors (TNF-α) and reactive oxygen species induced by lung ischaemia lead to cell apoptosis." (PMID 32586365, 2020). "Inhibition of the IL-1 receptor or TNF-α significantly reduces brain damage induced by ischemia, while the overexpression or treatment of IL-1 or TNF-α worsens ischemic damage." (PMID 32531881, 2020). "We also measured the expression of the astrocyte marker GFAP and pro-inflammatory factor TNF-α in the ischemia penumbra 24 h after reperfusion." (PMID 32917229, 2020). "We measured the expression of proinflammatory cytokines (IL-1β, IL-6, and TNF-α) in the ischemia penumbra 24 h after reperfusion." (PMID 32917229, 2020). "In the present study, we observed transient increases in pro-inflammatory cytokines, such as IL-1β, IL-6, and TNF-α in the spinal cord after ischemia, indicating inflammation." (PMID 33050051, 2020). "HLJDT was proven to reduce the production of proinflammatory factors including IL-1β, TNF-α, IL-6, as well as IL-17, thus it is of great significance in alleviating ischemia." (PMID 33613277, 2020). "In the rodent brain, ischemia-induced inflammation switches the TNF function from neuroprotective to neurotoxic." (PMID 33005129, 2020). "Transient forebrain ischemia significantly increased IL-1β and TNF-α levels in hippocampal homogenates, and cuprizone treatment aggravated the increase in IL-1β and TNF-α in the hippocampus after ischemia." (PMID 32531881, 2020). "In microglia, macrophages, and monocytes, the miR-155 expression induced in response to proinflammatory stimuli such as IFN-γ and TNF-α during ischemia-induced inflammation." (PMID 32937836, 2020). "Ginsenoside Rb1 can reduce the release of TNF-α and IL-6 in a rat model of bone pain caused by cancer and it can inhibit the expression of TNF-α and IL-6 induced by intestinal ischemia/reperfusion injury in rats." (PMID 32020864, 2020). "In ischemia models, a resuscitation with EtP reduced the local proinflammatory tumor necrosis factor (TNF) expression in liver, and improved survival by reducing mucosal hyperpermeability." (PMID 33117829, 2020). "Quantitative results of western blot demonstrated that the levels of TNFα, a pro-inflammatory cytokines, and cyclooxygenase-2 (Cox2), a key enzyme that mediates inflammatory signaling, were significantly higher in ischemia group vs. control." (PMID 32117296, 2020). "Proinflammatory agents, such as interleukin (IL)-6, IL-1, and TNF-α, promote the developing of the harmful phlogosis that takes place in the brain after the ischemia." (PMID 32899616, 2020).